PTX3 (pentraxin 3)
Diseases named in the same sentence as PTX3 in open-access papers (continued):
Sharing a sentence is not in itself a finding about the gene and the disease.
Sepsis (continued). "PTX3 in diagnosing sepsis does not appear to be superior to other biomarkers, like CRP and PCT." (PMID 25530683, 2014). "However, PTX3 has not previously been compared with PCT in the case of sepsis patients, although in many papers PCT has been shown to be a better prognostic marker than CRP." (PMID 23341967, 2013). "Neutrophils may therefore not be the only source of PTX3 during sepsis." (PMID 30687307, 2018). "The study correlated PTX3 levels with PCT and lactate, which are age-old markers established in sepsis, unlike other new markers." (PMID 36168379, 2022). "In the present study, both PTX3 and high PCT seemed to be independent predictors of severe sepsis while CRP did not." (PMID 23341967, 2013). "The median serum PTX3 concentration increased gradually when moving from SIRS without infection through sepsis, severe sepsis, and septic shock (Kruskall Wallis, p = 0.0001)." (PMID 24039869, 2013).
atherosclerosis (85 papers, 2010 to 2025). A disease characterized by the build-up of fatty material and calcium deposition in the arterial wall resulting in partial or complete occlusion of the arterial lumen. "PTX3 is implicated in atherosclerosis, acute coronary syndrome, and chronic heart failure, linking obesity, inflammation, and cardiovascular disease." (PMID 41562853, 2025). "Its levels rise in response to inflammation, injury, atherosclerosis, and infections, whereas low PTX3 levels are linked to atherosclerosis progression, vascular inflammation, and macrophage accumulation." (PMID 41562853, 2025). "PTX3 has been linked with heart failure and atherosclerosis, and elevated levels were found among patients with coronary artery disease (CAD)." (PMID 35888704, 2022). "PTX3 is likely to be an independent risk factor for the development of vascular events and atherosclerosis." (PMID 36574434, 2022). "The chronic endothelial dysfunction observed in patients with atherosclerosis and cardiovascular disease is associated with increased circulating PTX-3." (PMID 34439802, 2021). "This work implicates PTX3 levels correlated with local inflammation and the formation of atherosclerosis, and illustrates its association with lipid metabolism." (PMID 31998222, 2019). "More recently, it has been demonstrated that PTX3 deficiency is associated with increased atherosclerosis, macrophage accumulation and inflammation in the atherosclerotic lesions suggesting a modulation by PTX3 of the vascular associated inflammatory response." (PMID 29416668, 2018). "PTX3 deficiency in model mice (ApoE mice) was associated with atherosclerosis development and increased macrophage accumulation within atherosclerotic plaques as well as with more pronounced inflammatory profiles in vascular walls." (PMID 28536575, 2017). "Relative PTX3 deficiency in humans is associated with increased inflammation, cardiac damage, and atherosclerosis, while its overexpression limits carotid restenosis after angioplasty." (PMID 28536575, 2017). "Knockdown of PTX3 in apolipoprotein E-knockout mice is associated with cardiac damage, inflammation and atherosclerosis pointing to a protective effect of PTX3." (PMID 26842615, 2016). "Studies demonstrated that increased serum levels of C-reactive protein (CRP), interleukin (IL)-6, tumor necrosis factor (TNF)-α, and pentraxin (PTX)-3 are important risk factors for atherosclerosis, and cardiovascular diseases." (PMID 24481114, 2014). "Previous studies, including our own, have reported that various cell types associated with atherosclerosis and metabolic syndrome produce PTX3 in response to inflammatory signals, while the liver elaborates most circulating CRP." (PMID 24705587, 2014). "While PTX3 deficiency is associated with increased inflammation, cardiac damage, and atherosclerosis, the overexpression limits carotid restenosis after angioplasty." (PMID 23690668, 2013). "PTX3 has emerged as a key acute-phase protein associated with inflammation in cardiovascular disorders, including heart failure, atherosclerosis, acute coronary syndromes, and peripheral vascular diseases." (PMID 23690668, 2013). "The current study is the first to explore the association of PTX3 level with in vivo measurements of atherosclerosis in three independent population studies." (PMID 22319633, 2012). "In contrast, severity (atherosclerosis score) of carotid and femoral atherosclerosis was found to be independently and significantly associated with PTX3 level in the Bruneck Study." (PMID 22319633, 2012). "The literature indicates that PTX3 may modulate atherosclerosis and is associated with diabetic micro- and macrovascular complications." (PMID 40332236, 2025). "Pentraxin 3 is a protein implicated in endothelial dysfunction and atherosclerosis." (PMID 40095687, 2025).
atherosclerosis (continued). "For example, in another evaluation, it was stated that PTX-3 deficiency may be associated with increased inflammation and subsequently may cause cardiac damage and atherosclerosis." (PMID 38510866, 2024). "Interestingly, most of the genes involved in the triggering of inflammation and oxidative stress in PTX3-deficient ECs are regulated at the transcriptional level, and disease-specific gene expression profiles have been associated with atherosclerosis." (PMID 36362273, 2022). "Besides, studies shown that Tan IIA prevents endothelial inflammation by attenuating the expression of Pentraxin 3, a novel diagnostic biomarker for atherosclerosis, and Pentraxin 3 dependent monocyte adhesion to endothelial cells." (PMID 34819867, 2021). "Furthermore, in vivo studies showed that PTX3 is cardioprotective in acute myocardial infarction, while deficiency in this pentraxin promotes both vascular inflammation and atherosclerosis in mice." (PMID 31316299, 2019). "It is unclear whether high levels of PTX3 are a protective factor against atherosclerosis or a risk factor associated with the inflammatory process of atherogenesis." (PMID 31998222, 2019). "In passing, PTX3 deficient mice develop larger atherosclerosis." (PMID 29715313, 2018). "Thus, PTX3 deficiency is associated with increased inflammation, cardiac damage, and atherosclerosis." (PMID 26842615, 2016). "Although the presence of PTX3 in human atherosclerotic damage is well defined, its causal role in the onset and progression of atherosclerosis, remains unclear." (PMID 27559355, 2016). "On the other hand, the role of pentraxin-3 in pathogenesis of vascular pathology is still debated: some studies suggest a pathogenic role of PTX-3 in atherosclerosis, while other works lead to hypothesizing an atheroprotective effect." (PMID 26697221, 2015). "Our present findings support the theory that PTX3 may be a potentially modifiable risk factor for atherosclerosis and that adiponectin may provide potentially substantial clinical benefits in the stabilization of carotid plaques." (PMID 24936646, 2014). "The causal role of PTX3 in the pathogenesis of atherosclerosis remains obscure." (PMID 24705587, 2014). "Moreover, it has been demonstrated that the disruption of the internal layers of the vessel, after coronary stenting in patients with severe atherosclerosis, causes the increase of PTX3 plasma levels already after 15 minutes." (PMID 23690668, 2013). "Elevated levels of PTX3 were observed both in mice with atherosclerosis as well as in patients with acute coronary syndromes, predicting poor prognosis." (PMID 40573228, 2025). "In the same study, FGF23 and PTX3 levels, which are markers of atherosclerosis and endothelial dysfunction, respectively, were found to be higher in children with the homozygous M694V genotype." (PMID 40361895, 2025). "This protective role is also evident in atherosclerosis, where PTX3 reduces neutrophil adhesion and inflammation, thereby mitigating the progression of the disease." (PMID 40244022, 2025). "In prior studies, it was demonstrated that as a regulator of inflammatory response, PTX3 was involved in the progression of cardiovascular diseases, such as angiogenesis, atherosclerosis, extracellular matrix formation, and metabolic syndrome." (PMID 39657836, 2025). "The analysis of the impact of inclisiran on the subclinical inflammatory markers of atherosclerosis showed a statistically significant reduction in PTX3 in both groups." (PMID 40573228, 2025). "The involvement of pentraxin-3 (PTX3) in the pathophysiology of atherosclerosis especially concerns the modulation of the vascular inflammatory response and enhances endothelial cell damage." (PMID 40573228, 2025). "Pentraxin-3 is an acute-phase inflammation protein produced by several cell types, involved in EC dysfunction and atherosclerosis through various mechanisms." (PMID 37194071, 2023).
atherosclerosis (continued). "Increased levels of PTX3 reflect an increased vascular inflammatory status due to its direct synthesis by cells that are involved in atherosclerosis." (PMID 37374202, 2023). "Supporting this finding, patients with a homozygous M694V genotype had higher FGF23 and PTX3 levels, which are surrogate markers for atherosclerosis and endothelial dysfunction, respectively." (PMID 35629299, 2022). "In this perspective, the interplay between oxidative parameters and inflammation is a crucial issue because both MDA and hsCRP/PTX3 have contributed to endothelial dysfunction and atherosclerosis progression." (PMID 35743929, 2022). "Inflammatory markers, including CRP, IL-6, and Pentraxin-3, are used to monitor the atherosclerosis process in coronary artery disease." (PMID 33613306, 2021). "As a result, when considering its interactions with atherosclerosis conditions such as that occurring in acute ischemic stroke, PTX3 appears to be of superior prognostic value as compared to CRP in the LAA subgroup." (PMID 33210471, 2021). "FPR2-SAA interaction contributes to atherosclerosis progression also by promoting the secretion of long pentraxin 3 (PTX3), an essential component of innate immunity, in human aortic endothelial cells." (PMID 33804219, 2021). "HDL participate to inflammatory response also by promoting the production of the acute phase protein PTX3 by endothelial cells; PTX3, in turn, plays a double-edged sword role not only in infections, but also in atherosclerosis, thrombosis, and obesity." (PMID 33947039, 2021). "High levels of PTX3 have been found in plasma from patients with extensive atherosclerosis and increased LDL cholesterol." (PMID 31998222, 2019). "PTX3 is produced by different cell types potentially involved in atherosclerosis, in particular EC, smooth muscle cells and macrophages." (PMID 31057548, 2019). "While it has long been known that atherosclerosis is an inflammatory disease and consequently innate and adaptive immune responses are expected to play a role, the involvement of PTX3 in cardiac diseases is somewhat less evident." (PMID 31057548, 2019). "Recent work suggests that PTX3 is more specific for the development of atherosclerosis than other markers such as hs-CRP." (PMID 31998222, 2019). "Nevertheless, as for atherosclerosis, there is still some controversial views about the effect of PTX3 and its contribution to CVD and further investigation is required to assess its role, specifically in ESRD settings." (PMID 31316299, 2019). "Multiple clinical studies had confirmed that PTX-3 is closely related to the occurrence and prognosis of vulnerable plaques in atherosclerosis and acute coronary syndrome." (PMID 30992732, 2019). "Further studies are required to confirm the actual outcome of the balance between the pro- and antiatherogenic mechanisms of PTX3 in the development and/or progression of atherosclerosis in dialysis patients." (PMID 31316299, 2019). "PTX3 is stored in neutrophil granules on areas of atherosclerosis and released when neutrophils are exposed to TNF-α." (PMID 31998222, 2019). "We will focus on three newly identified atherosclerosis biomarkers in SLE: pentraxin-3 (PTX3), pro-inflammatory HDL (piHDL), and endocan." (PMID 29435447, 2017). "In keeping with this, in a double knockout mouse model for PTX3 and apolipoprotein E (ApoE), macrophages infiltration was enhanced, and a dramatic increase of atherosclerosis was reported." (PMID 27559355, 2016). "In fact, by using a cell model of atherosclerosis, it was shown that suppression of PTX3 reduces inflammation and apoptosis mediated by the IkB kinase (IKK)/IkB/nuclear factor-kB (NF-kB) pathway." (PMID 27559355, 2016). "Pentraxin-3 (PTX3) reportedly has protective roles in atherosclerosis and myocardial infarction, and is a useful biomarker of vascular inflammation." (PMID 28955836, 2016). "Recently, PTX3 has been proposed as a potential therapeutic target to limit the development of atherosclerosis." (PMID 27559355, 2016).
atherosclerosis (continued). "The link between PTX3 and complement system was confirmed by the occurrence of high PTX3 level within atherosclerosis-related coronary arterial thrombi that are mainly constituted by resident macrophages, neutrophils and foam cells." (PMID 27559355, 2016). "Recently, epidemiological and clinical data candidate PTX3 as a valid biomarker for atherosclerosis." (PMID 27559355, 2016). "It will be interesting to examine the role of the protein in complement activation during atherogenesis to define the specific role of PTX3 in the atherosclerosis." (PMID 27559355, 2016). "We also aimed to evaluate the relationship between PTX3 and atherosclerosis in patients with NAFLD, by measuring carotid femoral pulse wave velocity (cf-PWV), carotid intima media thickness (CIMT), and flow mediated dilatation (FMD)." (PMID 26997950, 2016). "Based on the kind of cell phenotype being recruited (macrophages and vascular cells), which is known to produce PTX3, this protein was investigated as a potential modulator of atherosclerosis." (PMID 27559355, 2016). "In the present review, we discuss the multifaceted effects of PTX3 on the cardiovascular system focusing on its involvement in atherosclerosis, endothelial function, hypertension, myocardial infarction and angiogenesis." (PMID 27559355, 2016). "While PTX3 was shown to be atheroprotective in experimental atherosclerosis, preliminary data in humans suggest that plasma levels of PTX3 are associated with the presence of atherosclerotic plaques and prevalent vascular disease." (PMID 25960621, 2015). "To date, several studies evaluated blood levels of two important inflammatory markers for atherosclerosis, such as IL-6 and PTX-3, among patients with HTN or OSA alone." (PMID 26697221, 2015). "Given the largely known role of IL-6 and PTX-3 as indicators for atherosclerosis, our results (also including the increased carotid IMT in OSA HTN subjects) suggest an additive effect of OSA and hypertension on the progression of endothelial impairment." (PMID 26697221, 2015). "The aim of this study was to evaluate the consequences of the coexistence of OSA and HTN on a marker of carotid atherosclerosis (such as IMT) and on inflammatory markers of atherosclerosis (such as IL-6 and PTX-3)." (PMID 26697221, 2015). "OSA and HTN have an additive role in the progression of carotid atherosclerosis and in blood levels of inflammatory markers for atherosclerosis, such as interleukin-6 and pentraxin-3." (PMID 26697221, 2015). "As such, a previous study confirmed an association between PTX3, CRP, LDL cholesterol and coronary artery disease severity in patients with intermediate-high atherosclerosis severity." (PMID 25014007, 2014). "Evidence suggests that PTX3 serves as a biomarker of inflammatory diseases, including atherosclerosis and metabolic disorders." (PMID 24705587, 2014). "The sustained PTX3 expression seen in irradiated arteries indicate that radiation-induced vascular inflammation shares similarities with atherosclerosis." (PMID 24060373, 2013). "PTX3 in humans, like CRP, correlates with surrogate markers of atherosclerosis and is independently associated with the risk of developing vascular events." (PMID 23690668, 2013). "The analysis of the predictive value of PTX3 levels on IMT progression, in addition to the association with IMT, is warranted to support the relevance of PTX3 as a marker of preclinical atherosclerosis." (PMID 23690668, 2013). "These contradictory observations advocate the need of a unifying study to unveil the exact role of PTX3 in the development or resolution of atherosclerosis." (PMID 23755050, 2013). "The potential role of PTX3 in atherosclerosis was recently addressed in PTX3/apolipoprotein E (ApoE) double knockout mice." (PMID 23690668, 2013). "So far a role for PTX3 was described in the context of angiogenesis, vascular restenosis, atherosclerosis, and myocardial infarction." (PMID 23690668, 2013).